TNF (tumor necrosis factor)
Diseases named in the same sentence as TNF in open-access papers (continued):
Sharing a sentence is not in itself a finding about the gene and the disease.
Alzheimer disease (continued). "For instance, levels of TNFα are elevated in patients suffering from Alzheimer’s disease (AD), major depression, multiple sclerosis (MS) and acute brain trauma and other encephalopathies." (PMID 35625761, 2022). "For example, higher levels of proinflammatory cytokines, such as interleukin (IL)-1β and IL-6, and tumor necrosis factor-α (TNF-α), have been observed in the blood, brain, and cerebral spinal fluid in patients with Alzheimer’s disease and Parkinson’s." (PMID 35055094, 2022). "For example, p38 MAPK activation via multiple pathways is necessary for the productions of IL-1, IL-6, TNF-α, COX-2, and iNOS, implying that p38 MAPK activity is associated with the hallmark lesions of Alzheimer’s disease." (PMID 35214883, 2022). "The combined application of ALC+quercetin in an animal model of Alzheimer's disease also significantly reduced hippocampus levels of inflammatory biomarkers, like TNF-α and IL-6." (PMID 35936217, 2022). "It was revealed that prolonged activation of microglia cells and the resulting overproduction of inflammatory factors, including IL-6, IL-1β, and TNF-α, were significant contributions to the development of Alzheimer's disease." (PMID 36147643, 2022). "TNF-α, a potent pro-inflammatory cytokine generated in response to various neurological disorders like Alzheimer’s disease (AD), Parkinson’s disease (PD), and Multiple Sclerosis (MS), is an eminent regulator of the sphingomyelin metabolic pathway." (PMID 36060699, 2022). "In neurodegenerative diseases, such as Alzheimer’s disease (AD), multiple sclerosis, and Parkinson’s disease (PD), the levels of TNF are increased in the post-mortem brain, serum, and cerebrospinal fluid (CSF)." (PMID 36428505, 2022). "Further, the administration of vitamin C (200 and 400 mg/kg body weight) can restore colchicine induced memory impairments and also decrease hippocampal TNF-α and IL-1β concentrations in colchicine induced Alzheimer’s disease rats." (PMID 35866081, 2022). "Tumor necrosis factor alpha (TNF-α) plays a vital role in Alzheimer’s disease (AD) pathology, and TNF-α inhibitors (TNFIs) modulate AD pathology." (PMID 36297637, 2022). "Several cytokines (IL-1β, IL-6, TNF-α, IL-8 and IL-15) were further raised in Alzheimer’s disease with systemic infection." (PMID 33723589, 2021). "A recent study stated that donepezil incorporated into PLGA in the presence of Pluronics F68 caused a significant dose-dependent decrease in both gene and protein expression levels of IL-1β, IL-6, GM-CSF and TNF-α in Alzheimer’s disease." (PMID 34502328, 2021). "Suggested by previous studies, using small molecule inhibitors to modulate TNF‐α has the potential for preventing and treating Alzheimer's disease, and the increased expression level of iNOS in activated microglia contributes to neurodegeneration." (PMID 33942523, 2021). "We found that 38 genes showed consistent changes in astrocytes in Alzheimer’s disease, multiple sclerosis, poly I:C treatment, and TNFα treatment (25 genes were upregulated and 13 genes were downregulated by diseases and treatments)." (PMID 34172753, 2021). "Tumor necrosis factor-α (TNF-α) plays a central role in Alzheimer’s disease (AD) pathology, making biologic TNF-α inhibitors (TNFIs), including etanercept, viable therapeutics for AD." (PMID 34972522, 2021). "Anti-inflammatory agents like enetercept (a TNFα inhibitor approved for several types of arthritis) have been suggested to treat Alzheimer’s disease." (PMID 32670015, 2020). "Phosphorylated STAT3, TNFα, and IL-6 were also downregulated in the presence of anatabine in a transgenic mouse model of Alzheimer’s disease." (PMID 32855621, 2020). "In Alzheimer's disease sphingolipids are involved in the processing and aggregation of β-amyloid and in the transmission of the cytotoxic signal β-amyloid and TNFα-induced." (PMID 32528400, 2020).
Alzheimer disease (continued). "In contrast, our retrospective case study which used conversion to Alzheimer’s disease or dementia as an outcome measure suggests the potential neuroprotective benefit of interrupting TNF signaling between the periphery and the brain." (PMID 32203525, 2020). "Blood concentrations of VCAM-1, TNFα, and IL-6 are higher in people with Alzheimer’s disease compared to healthy individuals." (PMID 32670015, 2020). "It is reported that Alzheimer's disease is progressed by activated microglia, the resident brain macrophage, and release inflammatory mediators such as TNF-α." (PMID 32908940, 2020). "High levels of IL-1, IL-6, CRP, and TNF-α were also found to be potentially predictive markers for the development of Alzheimer's disease (AD) or cognitive decline." (PMID 32257550, 2020). "Tumor necrosis factor-α (TNF-α) is a pro-inflammatory cytokine, involved in Alzheimer’s disease pathogenesis." (PMID 32457323, 2020). "For example, up-regulation of TNF-α is associated with deficits of memory and synaptic plasticity in Alzheimer's disease, and inhibition of TNF-α is effective for treating the disease." (PMID 31297084, 2019). "Some researchers reported that the pro-inflammatory marker TNF-α increased in the peripheral blood or CSF of patients suffering from Alzheimer’s disease." (PMID 31039131, 2019). "As neuroinflammation is involved in neurodegenerative diseases, the data also shed some lights on the role of TNF‐α on some aspects of neurodegenerative diseases, including Parkinson's disease and Alzheimer's disease." (PMID 31386303, 2019). "A previous study reported that peripheral TNF-α modulates amyloid pathology by regulating blood-derived immune cells trafficking in a transgenic mouse model of Alzheimer’s disease." (PMID 31398905, 2019). "In a mouse Alzheimer’s disease model, a recent study demonstrated positive correlation between Beclin-1, IL-1β, and TNF-α (tumor necrosis factor alpha) in the cortex and/or hippocampus, suggesting a relationship between inflammatory responses and autophagy." (PMID 31295858, 2019). "Animal studies have provided some clearer understanding of the role of TNF-α in Alzheimer’s disease with evidence of disease modulation with the use of anti-TNF agents." (PMID 29686666, 2018). "It is well-established that IP-10, RANTES, and TNFα are significantly increased in Alzheimer’s disease (AD), Parkinson’s disease (PD), Multiple Sclerosis (MS), HIV-associated dementia and Neuropathic Pain Syndrome96–115." (PMID 30401897, 2018). "On the contrary, several studies have reported that activation of MC4R obviously inhibited the overexpression of TNF-α, IL-6, and IL-1β in cerebral ischemia, Alzheimer’s disease, and subarachnoid hemorrhage." (PMID 29642894, 2018). "Secondly, our findings support previous postulation that the levels of peripheral TNF- α was found to be significantly lower in mild to moderate Alzheimer’s disease as compared to severe Alzheimer’s disease." (PMID 30104698, 2018). "In genetic studies, the A allele of TNF-α 308 G/A gene associated with risk for MI, whereas TNF-α polymorphisms and TNF-α itself, have been variably associated with increased Alzheimer’s disease risk." (PMID 29686666, 2018). "An increase in neuroinflammatory markers such as nitric oxide, interleukin-1β (IL-1β) and tumor necrosis factor (TNF-α) has been widely reported in brains of both Alzheimer’s disease patients and transgenic AD models." (PMID 30340518, 2018). "Our data show that several molecular targets and signaling pathways induced by TNFα in neurons resemble those seen in Alzheimer's disease pathology." (PMID 28947966, 2017). "Levels of the proinflammatory cytokines IL-6, IL-1β, and TNF-α were significantly increased in AD mice compared with WT mice, confirming that inflammation is an important characteristic of Alzheimer’s disease." (PMID 28106117, 2017).
Alzheimer disease (continued). "The clinical study also reported that the levels of TNF-α and IL-1β in blood and cerebrospinal fluid of patients with Alzheimer's disease were significantly higher compared with general population." (PMID 29190943, 2017). "CBD provoked a reduction in TNF-α release and NF-κB expression in the animal model of Alzheimer disease." (PMID 28539998, 2017). "Tumour necrosis factor-alpha (TNF-α) produced by activated microglia plays a critical role in the induction of neuronal death in Alzheimer’s disease." (PMID 28399892, 2017). "A reduction of brain TNF-α levels was also described in an animal model of Alzheimer disease (AD) exposed to EX-4 treatment." (PMID 28932183, 2017). "In other studies, increased levels of TNF-α and IL-1β were found in the cerebrospinal fluid and plasma in patients with Alzheimer’s disease." (PMID 26432692, 2016). "TNFα concentrations are also elevated in several brain disorders including multiple sclerosis, Alzheimer's Disease, Parkinson's Disease, ischemia, and traumatic brain injury." (PMID 27812316, 2016). "The levels of pro-inflammatory cytokines, such as tumor necrosis factor-α (TNF-α), interleukin-6 (IL-6), are elevated in Alzheimer’s disease (AD) brains." (PMID 27287266, 2016). "With tumor necrosis factor α being an important proinflammatory cytokine, a recent trial investigated the effect of the tumor necrosis factor α inhibitor etanercept after peripheral administration in patients with Alzheimer’s disease." (PMID 26560086, 2015). "The brains of patients with Alzheimer's disease (AD) present elevated levels of tumor necrosis factor-α (TNFα), a cytokine that has a dual function in neuronal cells." (PMID 25675299, 2015). "Recent work has shown how TNF inhibitor therapy in people with RA is protective for Alzheimer's disease." (PMID 25414636, 2014). "Alzheimer's disease cortex showed significantly increased mRNA and protein levels of IL-1β, TNFα, GFAP, CD11b, cPLA2 IVA sPLA2 IIA COX-1 and COX-2, but decreased levels of pre-synaptic synaptophysin (SYP) and post-synaptic drebrin (DBN1)." (PMID 25329999, 2014). "Wnt5a was upregulated in the Alzheimer’s disease mouse brain due to β-amyloid peptide, inducing neuroinflammation and neurotoxicity via inflammatory cytokines IL-1β and TNF-α." (PMID 24993819, 2014). "This has lead to a move toward considering anti-TNFα as a therapy for Alzheimer's dementia Auanofin, a gold—containing medication and established treatment for RA, dampens inflammation through manipulation of the anti- and pro-inflammatory interleukin balance." (PMID 25414636, 2014). "JWH133 reduced expression of active p38 MAPK, JNK, and proinflammatory cytokines (IL-1β, IL-6, and TNF-α) induced cognitive improvement in a genetic mice model of Alzheimer's disease." (PMID 24963491, 2014). "Many genetic factors have been shown to play etiological roles in diverse mental disorders, including PGBD1 in schizophrenia and Alzheimer’s disease and TNFα in schizophrenia and bipolar disorder." (PMID 23437227, 2013). "Activation of TLR4 is reported to be associated with increased production of TNF-α and IL-1β in the CNS of APPswe/PS1 transgenic mice, a mouse model of Alzheimer’s disease (AD)." (PMID 23234315, 2012). "Astrocyte activation and overexpression of cytokines and chemokines like IL-1β, TNF-α and CXCL8 have been associated with Alzheimer’s disease." (PMID 23029125, 2012). "TNF-α, a pleoprotic proinflammatory cytokine, is upregulated in several neurodegenerative disorders including multiple sclerosis, Parkinson disease, Alzheimer disease, multiple sclerosis, and in optic nerve microglia and astrocytes in glaucoma patients." (PMID 22509108, 2012). "In accord with this, rapid clinical improvements in cognitive function have been described in subjects with Alzheimer's disease following intraspinal administration of the TNF-α-blocking agent etanercept, followed by Trendelenburg positioning." (PMID 22277195, 2012).
Alzheimer disease (continued). "TNFα can mediate cell death but, conversely, TNFα is thought to enhance neuroprotective processes in models of acute neurodegeneration (ischemia, excitotoxicity, axotomy) and chronic (Alzheimer's disease) neurodegeneration." (PMID 21143912, 2010). "Recent reports of rapid clinical improvement in patients with Alzheimer's disease and related forms of dementia following perispinal administration of etanercept, a TNF antagonist, suggest that etanercept also has the ability to reach the brain CSF." (PMID 19284700, 2009). "Excess tumor necrosis factor-alpha (TNF) has been identified as a therapeutic target in Alzheimer's disease (AD)." (PMID 19284700, 2009). "Animal models of Alzheimer's disease, such as the APP transgenic line Tg2567 carrying the Swedish mutation, also show enhanced levels for TNF-α, IL-1β, IL-1α, chemoattractant protein-1, COX-2 and complement component 1q." (PMID 18564425, 2008). "The concept of TNF-alpha-inhibition for the treatment of Alzheimer's disease has been recently reviewed, and is supported by additional recent publications." (PMID 18184433, 2008). "The efficacy of etanercept, a biologic antagonist of TNF-alpha, delivered by perispinal administration, for treatment of Alzheimer's disease over a period of six months has been previously reported in a pilot study." (PMID 18184433, 2008). "These experimental findings, together with the rapid effects of perispinal etanercept shown here, converge to suggest that synaptic dysregulation produced by excess TNF-alpha contributes to cognitive and behavioral dysfunction in Alzheimer's disease." (PMID 18184433, 2008). "Increasing basic science, genetic, and clinical evidence now supports the concept that excess TNF-alpha plays a central role in Alzheimer's disease." (PMID 18184433, 2008). "Involvement of the pro-inflammatory cytokine tumor necrosis factor-alpha (TNF-alpha) in the pathogenesis of Alzheimer's disease has long been suspected." (PMID 18184433, 2008). "These caveats notwithstanding, the scientific rationale for the further investigation of anti-TNF-alpha treatment of Alzheimer's disease is compelling, with supporting genetic, epidemiologic, clinical, and basic science evidence." (PMID 18644112, 2008). "Pilot evidence supporting the efficacy of anatomically targeted anti-TNF-alpha treatment for Alzheimer's disease has recently been published." (PMID 18184433, 2008). "Substantial basic science and clinical evidence suggests that excess tumor necrosis factor-alpha (TNF-alpha) is centrally involved in the pathogenesis of Alzheimer's disease." (PMID 18184433, 2008). "The case presented here provides clinical evidence of a rapidly reversible, TNF-alpha-related component to the cognitive dysfunction present in Alzheimer's disease." (PMID 18184433, 2008). "Therefore, it is of interest to investigate the role of tumor necrosis factor-alpha (TNF-α) in Alzheimer's disease (AD) by analyzing its relationship with brain atrophy and cognitive decline in 80 AD patients." (PMID 41960503, 2026). "Moreover, thymol demonstrated dose-dependent anti-inflammatory effects in an Alzheimer’s disease model, significantly reducing serum and hippocampal levels of IL-1, IL-6, TNF-α, and COX-2, with optimal effects at 80 mg/kg." (PMID 40430456, 2025). "Microglia, the brain’s resident immune cells, become chronically activated, releasing cytokines such as interleukin (IL)-1β, IL-6, and tumor necrosis factor-alpha (TNF-α) that promote amyloid-β aggregation and tau hyperphosphorylation, both central features of Alzheimer’s disease." (PMID 41230326, 2025). "For instance, a combination of N-acetylcysteine (NAC) and curcumin significantly reduced oxidative damage and neuroinflammation in models of Alzheimer’s disease by lowering neuronal apoptosis, lipid peroxidation, and pro-inflammatory cytokines such as TNF-α and IL-1β." (PMID 41002745, 2025).
Alzheimer disease (continued). "Moreover, patients with Alzheimer's disease, the most common type of dementia, have high TNF-α levels, and perispinal etanercept (a TNF inhibitor) has been shown to rapidly improve verbal fluency and aphasia in patients with Alzheimer's disease." (PMID 40291023, 2025). "Specifically, Lut has been shown to inhibit inflammatory responses by reducing the expression of the pro-inflammatory cytokines tumor necrosis factor (TNF)-α, IL-1β, and IL-6 and has demonstrated efficacy in the treatment of neutrophilic asthma, lupus nephritis, and Alzheimer’s disease." (PMID 39861331, 2025). "Similarly, epicatechin was found to reduce tumor necrosis factor-alpha TNF-α release in an Alzheimer’s disease mouse model, supporting its neuroprotective potential." (PMID 41011572, 2025). "Similarly, individuals affected by Alzheimer’s disease exhibit hypomethylation of pro-inflammatory genes such as TNFα and Il6, potentially contributing to neuronal damage and chronic neuroinflammation." (PMID 40867210, 2025). "Functional enrichment analysis revealed marked associations of the DEGs with major neurodegenerative disorders [PD, Huntington’s disease, and Alzheimer’s disease (AD)], potentially mediated through impaired oxidative phosphorylation and aberrant tumor necrosis factor (TNF) signaling." (PMID 40862055, 2025). "For example, in Alzheimer’s disease (AD), the aberrant accumulation of β-amyloid specifically activates intracellular inflammasomes, contributing to the overproduction of the pro-inflammatory factors IL-1β and TNF-α, which impair synaptic signaling efficiency." (PMID 40430556, 2025). "GL can improve LMI mainly by 10 active ingredients in it, and they may play a role by regulating Alzheimer’s disease pathway and TNF protein." (PMID 38904095, 2024). "In contrast, upregulated genes were associated to disease-related pathways such as Parkinson's and Alzheimer's disease, as well as inflammatory pathways (i.e., TNFα and NF-kappa β signaling) in serum-cultured astrocytes, confirming their inflammatory secretory phenotype." (PMID 38915876, 2024). "Moreover, enriched KEGG pathways in cortex were found related to Alzheimer’s disease, TNF and IL-17 signaling pathways, among others." (PMID 39100749, 2024). "Inflammatory cytokines TNF-α and IL-6 secreted by microglial M1 macrophages and Angptl2 have been shown to induce neuroinflammation and participate in the progression of neurodegenerative diseases, such as Alzheimer’s disease." (PMID 38785563, 2024). "An inhibitor, chemically similar to AD-16, successfully suppressed the increase of IL-1β and TNF-α levels in an Alzheimer’s disease model, suggesting that AD-16 could also modulate this pathway." (PMID 39736920, 2024). "Experimental studies have shown that diabetic patients release pro-inflammatory cytokines such as IL-1β, IL-6, and TNF-α, which may lead to neuronal death and accelerate neurodegenerative changes in Alzheimer’s disease (AD)." (PMID 39157774, 2024). "A1-like astrocytes were found to be induced by the cytokine trio Il-1α, TNF, and C1q secreted by microglia and were identified in post-mortem samples from patients suffering from Alzheimer's disease (AD), Parkinson's disease (PD), amyotrophic lateral sclerosis (ALS), and multiple sclerosis (MS)." (PMID 37153637, 2023). "Furthermore, in the hippocampus, evodiamine significantly reduces neuroinflammation (TNF-α, IL-1β, and IL-6) and glial cell activation, rendering it a potential treatment for neurodegenerative diseases such as Alzheimer's disease." (PMID 37497547, 2023). "TNF-α is a key pro-inflammatory cytokine in Alzheimer’s disease." (PMID 36544525, 2022). "The enrichment analysis results of KEGG database indicated that KO significantly altered the pathways in inflammation and disease, such as nonalcoholic fatty liver disease, Parkinson disease, Huntington disease, Alzheimer disease, and the TNF signaling pathway." (PMID 35910841, 2022).